YY2 (YY2 transcription factor)
Diseases named in the same sentence as YY2 in open-access papers (continued):
Sharing a sentence is not in itself a finding about the gene and the disease.
tumor (continued). "Furthermore, our study revealed that YY2 suppressed dynamin‐related protein 1 (DRP1)‐mediated mitochondrial fission, which led to depletion of the liver CSC pool and subsequent decrease in tumor‐initiating capability." (PMID 37300334, 2023). "Furthermore, it is revealed that YY2 overexpression suppressed liver CSC asymmetric division, leading to depletion of the CSC pool and decreased tumor‐initiating capacity." (PMID 37300334, 2023). "To elucidate the pathological function of the YY2/DRP1 pathway in vivo, especially in regulating tumor‐initiating capacity, we established stable HCC‐LM3/pcCon, HCC‐LM3/pcYY2, and HCC‐LM3/pcYY2/pcDRP1 cell lines, and transplanted them subcutaneously into BALB/c‐nu/nu mice." (PMID 37300334, 2023). "Together, these results pointed to enrichment of YY2‐downregulated cells in stem‐like tumor spheres, suggesting a negative correlation between YY2 and CSCs." (PMID 37300334, 2023). "Furthermore, DRP1 overexpression prevented alterations in mitochondrial morphology observed upon YY2 overexpression, and partially restored the OCR in stem‐like tumor spheres formed by YY2‐overexpressed HCC‐LM3 cells." (PMID 37300334, 2023). "Meanwhile, in vivo limiting dilution assay (LDA) performed by xenograft experiment using a series of cell amounts as indicated revealed that YY2 overexpression decreased liver CSC frequency by > 10‐fold, as well as the expression of CSC markers CD44 and EpCAM in the xenografted tumor lesions." (PMID 37300334, 2023). "Together with the affinities of YY1 and YY2 to SLC7A11 promoter, which also need to be elucidated, the change in YY1 and YY2 levels is crucial for the overall outcome of the ferroptosis level in tumor." (PMID 35246964, 2022). "Furthermore, YY2 and YY1 bind competitively to the same DNA binding site in the SLC7A11 promoter and antagonistically regulate tumor cell ferroptosis, thus suggesting the molecular mechanism underlying their opposite regulation on tumorigenesis." (PMID 35246964, 2022). "YY2 competes with YY1 in binding to the AES promoter, and as YY1 is abundantly expressed in tumour cells, it is enriched in the AES promoter region and could disturb YY2‐mediated AES transcription." (PMID 32969187, 2020). "Moreover, YY2 overexpression, which resulted in a higher rate of chromosome missegregation, further increased anti‐PD‐L1 antibody treatment‐induced CTL infiltration into tumor lesions formed by MSI or MSS CRC cells." (PMID 39903759, 2025). "Furthermore, we show that YY2/BUB1B axis‐induced mitotic checkpoint hyperactivation triggers chromosome missegregation and cytosolic dsDNA, thereby inducing cytosolic dsDNA response and promoting tumor immunity." (PMID 39903759, 2025). "This study reveals that YY2 high expression‐mediated chromosome missegregation/micronuclei formation triggers pyroptosis and CTL activation by activating AIM2/caspase‐1/GSDMD cytosolic dsDNA response, and YY2/anti‐PD‐L1 combinatorial anti‐tumor therapeutic strategy." (PMID 39903759, 2025). "Heatmap analysis of gene expression in adherent cells and stem‐like tumor spheres revealed a negative correlation between YY2 and stem‐related factors, including CD44, SOX9, SALL2, KLF15, OCT4 (also known as POU class 5 homeobox 1 or POU5F1), MYC, ASCL1, and POU3F2." (PMID 37300334, 2023). "Furthermore, while YY2 overexpression suppressed liver CSC asymmetric division and promoted its symmetric division into two non‐CSC cells in stem‐like tumor spheres formed by HCC‐LM3 cells, DRP1 overexpression restored asymmetric division and blocked the symmetric one." (PMID 37300334, 2023). "YY2 competes with YY1 to bind to SLC7A11 promoter and regulates it antagonistically, resulting in the opposite regulation on glutathione synthesis, ferroptosis, and tumor progression, indicating that YY2/YY1 homeostasis is crucial for maintaining redox homeostasis in tumors." (PMID 35246964, 2022).
tumor (continued). "Interestingly, the roles of YY2 in tumorigenesis are antagonistic to those of YY1, suggesting that YY2 might be a potential tumour suppressor." (PMID 32969187, 2020). "YY2 overexpression robustly suppressed CRC cell proliferation, as indicated by the decrease in EdU‐positive cells, while increasing the cell death rate, suggesting that YY2 may exert its tumor suppressive function most plausibly by decreasing cell proliferation and promoting cell death." (PMID 38682484, 2024). "Unlike YY1, YY2 expression is downregulated in tumor tissues, and might act as a tumor suppressor." (PMID 32226547, 2020). "Moreover, while knocking out YY2 alone did not induce cell death and even benefits tumor cell proliferation, treatment with reversine, which could further weaken SAC activity as indicated by the shortened mitotic time, increased CIN as well as cell death in HCT116YY2KO cells." (PMID 38682484, 2024). "However, while recent studies have provided further evidence of the tumor suppressive role of YY2 as opposed to the protooncogenic role of YY1, no studies have suggested that they could regulate common binding site in the same target gene antagonistically and exert opposite functions." (PMID 35246964, 2022). "To test this possibility, we obtained residual tumor cells from CRC cells infected with TetOn‐YY2 lentivirus by sorting living cells that survived oxaliplatin treatment, treated them with or without doxycycline to induce YY2 overexpression, and examined their viability under oxaliplatin treatment." (PMID 38682484, 2024).
cancer (12 papers, 2017 to 2025). A tumor composed of atypical neoplastic, often pleomorphic cells that invade other tissues. "Significantly, YY2 somatic mutations found in cancer were shown to alter K247 methylation, DNA-binding activity and its regulated gene transcription, suggesting a potential role of YY2 K247 methylation in pathological conditions." (PMID 29098080, 2017). "In addition, YY2 somatic mutations found in cancer altered K247 methylation, its DNA-binding activity and its regulated gene transcription." (PMID 29098080, 2017). "While clinical data regarding YY2 are still limited, C343R, G317C, and K263N mutations in zinc‐finger domains of YY2 as potentially found in cancer patients cancelled the YY2 regulatory effect on SLC7A11 expression." (PMID 35246964, 2022). "To further elucidate the molecular mechanism underlying the regulatory roles of YY2 on cell cycle progression, we next investigated the effect of YY2 expression level on the transcriptional activity of p21 in zvarious cancer cell lines." (PMID 28903375, 2017). "Recent studies reported that YY2 might regulate the expression of these immunoregulatory cytokines, suggesting the possible role of YY2 in immune activity in carcinoma." (PMID 32969187, 2020). "Therefore, it will be valuable to investigate whether YY2 expression and hence K247 methylation described in the present study are also dynamically regulated in cancers." (PMID 29098080, 2017). "The prognostic model incorporates genes, such as YY2, PDHA1, SDC3, PPP2CB, and PDK3, all of which have been previously reported to influence cancer prognosis." (PMID 41235100, 2025). "Ets1, YY2 and JDP2 all contribute to cancer cell proliferation, invasiveness, EMT, drug resistance and neo-angiogenesis by regulating gene transcription." (PMID 36497433, 2022). "Our DNA-methylation-based predictors selected CpG sites and CGIs related to genes previously found individually involved in cancer development and with transcriptional activity regulated by methylation (e.g. MBTPS2, YY2, ECRG4, IKZF1)." (PMID 31708973, 2019).
cardiovascular diseases (3 papers, 2020 to 2023). "Given that ferroptosis also plays a crucial role in cardiovascular disease and neurological disorders, our results indicate the possibility that the YY2/ferroptosis axis might also regulate other biological processes and pathological conditions." (PMID 35246964, 2022). "Previous studies have shown that YY1 plays an important role in maintaining adult cardiac function and in cardiac disease development, but whether YY2 has any role in cardiovascular disease remains unknown." (PMID 32195266, 2020). "Although the bioactivity of YY2 has been previously studied, its role in cardiovascular diseases is not known." (PMID 32195266, 2020). "However, whether YY2 plays a role in cardiovascular diseases had not been previously explored in vivo." (PMID 32195266, 2020).
cardiac disease (1 paper, 2020). "However, whether YY2 has a role in cardiac disease is not known." (PMID 32195266, 2020).
YY2 also shares sentences with these, for which no sentence is quoted: branchiooculofacial syndrome (1 paper); cardiomyopathy (1); esophageal adenocarcinoma (1); glioblastoma multiforme (1); hepatocellular carcinoma (1); lung squamous cell carcinoma (1); neuroblastoma (1); neurological disorders (1); prostate adenocarcinoma (1); rectal cancer (1); skin cancer (1).